IL6 (interleukin 6)
Diseases named in the same sentence as IL6 in open-access papers (continued):
Sharing a sentence is not in itself a finding about the gene and the disease.
dry eye (continued). "The activated kinases initiate a cascade of protein phosphorylation involving multiple kinases and activate nuclear transcription factors, such as NF-KB, e.g., that the expression levels of TNF-α, IL-1β, and IL-6 were downregulated in BAC-induced dry eye after treatment with KIOM-2015E." (PMID 36499298, 2022). "We found that the phosphorylation of ERK and the expression of AQP5 were significantly elevated in the hyperosmotic-condition-induced dry eye cell model, as well as the inflammatory IL-6, IL-8 and TNF-α, which promote the inflammatory response and apoptosis of cells." (PMID 36232498, 2022). "The level of TNF-α significantly increased at 1 month (p = 0.031) and returned to the baseline level at 3 months postoperatively in subjects with dry eye; at 6 months postoperatively, the levels of IL-6 and IL-8 declined slightly but were still higher than the baseline levels (p = 0.004, p = 0.047)." (PMID 34957146, 2021). "The increase in IL-6 in our data is considered to be one of the processes in dry eye and may serve to explain the thinning of the cornea, the increased apoptosis, the reduced tear volume, the increased ocular pressure and the retinal injury." (PMID 32674521, 2020). "Indeed, the ocular surface status in dry eye is affected by the pro-inflammatory mediators such as IL-1, IL-6, TGF-β, TNF-α, and MMP-9; neurotrophic factors such as NGF; and antigen-presenting cells." (PMID 32698387, 2020). "Interleukin-6 (IL-6) is an important factor for corneal inflammation in in vitro dry eye models." (PMID 32674521, 2020). "In addition to the better-known inflammatory function of IL-2 and IFN-γ, there has been observed increases of the pro-inflammatory cytokine IL-6 in dry eye patients." (PMID 29235530, 2017). "Overexpression of IL-6 in dry eye patients correlates with the symptomatic severity of disease." (PMID 28248962, 2017). "IL-6 levels in the tear are significantly increased in dry eye patients." (PMID 27047687, 2016). "This indicated that IL6 could be one of the important cytokines affecting the pathogenesis of dry eye." (PMID 27555966, 2016). "The expression and production of IL-6 are also elevated in experimental dry eye models." (PMID 27047687, 2016). "Dry eye also induces the secretion of cytokines such as IL6, IL-1β, TNF-α, and IFN-γ." (PMID 27555966, 2016). "The expression of MMP9 and IL6 in dry eye patients may indicate that inflammatory mechanisms play a synergistic role in the development of the disease." (PMID 26221061, 2015). "Moreover, elevated levels of IL-6 have been observed in the tears of patients suffering from dry eye, ocular chemical injury and contact lenses wear." (PMID 25211490, 2014). "COX-2, MMP-9, and IL-6 expression are elevated in the cornea of dry eye." (PMID 23049824, 2012). "Expression of HO-1, COX-2, MMP-2, MMP-9, and IL-6 increased markedly in the dry eye group." (PMID 23049824, 2012). "IL-6 and IL-8 have been shown to be increased in the tears of dry eye patients in multiple studies." (PMID 20824100, 2010). "Finally, we explored whether pharmacological blockade of NF‐κB or IL‐6 pathways could alleviate delayed wound healing and nerve regeneration defects under dry eye conditions." (PMID 41208970, 2025). "Also, HL036, a molecularly engineered TNF Receptor 1 fragment, improves corneal staining, reduces ocular discomfort, suppresses lacrimal inflammation, decreases corneal inflammation, and improves goblet cell counts by suppressing IFN-γ, IL-21, and IL-6 in a dry eye-induced C57BL/6 mice model." (PMID 38399390, 2024). "Both IL-1β and IL-6 are proinflammatory cytokines that are secreted on the ocular surface in response to various pathologic stimuli, such as benzalkonium chloride-induced dry eye, desiccating stress induced dry eye, and microbial infections, such as P. aeruginosa, O. volvulus, or HSV-1." (PMID 27517861, 2016).
dry eye (continued). "Therefore, in dry eye patients, IL6 could be a biologic marker, and regulating IL6 though the IL6/JAK/STAT3 signaling pathway could be an effective therapeutic target." (PMID 27555966, 2016). "A previous study showed that blocking IL6 could increase goblet cells in conjunctival epithelium and reduce inflammatory cells, which could soothe the symptoms and prevent the chronic progression of dry eye." (PMID 27555966, 2016). "A study showed lowered levels of IL-1β, IL-6, and TNF-α in dry eye participants after treatment with topical cyclosporine tds." (PMID 40565378, 2025). "Elevated tear levels of IL-6 and MMP-9 have been reported in both KC and dry eye, suggesting shared inflammatory pathways influencing corneal remodeling and tear instability." (PMID 41302278, 2025). "In a murine model of dry eye, these nanocomplexes significantly reduced inflammatory markers, including TNF-α, ICAM-1, VCAM-1, MMP-2, MMP-9, IL-17, IL-1β, and IL-6, thereby underscoring their therapeutic utility in DED." (PMID 41300436, 2025). "Our LPA analysis found that IL-6 and IL-8 were higher in subgroup 1 that had more severe dry eye signs, while IL-10, IL-17A, and IFN-γ were higher in subgroup 2 that had less severe dry eye signs." (PMID 38177232, 2024). "Elevated levels of pro-inflammatory factors such as IL-1, IL-6, IFN-γ, and IL-17 have been observed in clinical and animal models of dry eye." (PMID 38898418, 2024). "They increased the expression of inflammatory genes (e.g., IL-6) and reduced mucin production genes (e.g., MUC16), reflecting dry eye characteristics." (PMID 38379013, 2024). "For example, increases in the concentrations of inflammatory cytokines, such as IL-1B, Il-6, IL-8, and tumor necrosis factor-α (TNF-α), in tears are correlated with clinical indices of dry eye." (PMID 39596346, 2024). "IL-6, IL-1β, and TNF-α play important roles in ocular inflammation; dry eye increases the levels thereof." (PMID 38139321, 2023). "Remarkably, we found that the levels of IL-6, IL-1β, and TNF-α increased in the corneas of dry eyes but significantly decreased after multi-wavelength LED treatment; these cytokines thus contribute to dry eye inflammation." (PMID 38139321, 2023). "The expression of inflammatory factors such as IL-1β, IL-6, IL-8, TNF-a and IFN-γ and infiltrated inflammatory cells, has been shown to be increased on the ocular surface of dry eye patients." (PMID 35812407, 2022). "Topical administration of MSCs has been shown to significantly decrease CD4, IL-1, IL-6, and tumor necrosis factor-alpha (TNF-α) levels in dogs affected by keratoconjunctivitis sicca." (PMID 36290184, 2022). "In vitro studies have demonstrated that atorvastatin downregulates T helper cells and thereby decreases inflammatory cytokines such as IL-1β, IL-6, IL-17 and IFN-γ, which are elevated in blepharitis and dry eye patients." (PMID 35372440, 2022). "The greatest differences are seen in neutrophils, myeloid (macrophage and monocyte) and cDC2 cells and include IL-6, LPS-stimulated MAPK, NFkB, IL-17, and PPARα/RXRα signaling pathways that contain mediators relevant to dry eye pathogenesis." (PMID 35402439, 2022). "The mRNA and protein levels of cGAS, STING, TBK1, IRF3, NF-κB and inflammatory cytokines (INF-α/β, IL-6 and CXCL10) in the cornea of normal and dry eye mouse models will be detected by PCR and Western blot." (PMID 35812407, 2022). "The areas under the curves of IL-1, IL-6, and TNF-α were 0.801, 0.800 and 0.736, respectively, indicating that IL-1, IL-6, and TNF-α in tears of patients with xerophthalmia have a high predictive value in efficacy." (PMID 35130850, 2022). "Significant differences in the concentration of cytokines (IL-6, IL-10, and TNF-α) were detected in tear samples collected from patients with dry eyes." (PMID 34659636, 2021).
dry eye (continued). "Proinflammatory cytokines IL-1, IL-6, IL-8, and HLA-DR activators TNF-α and IFN-γ were shown to be strongly correlated with dry eye markers, leading to ocular surface damage and goblet cell reduction." (PMID 34957146, 2021). "Disruption of the tear film can lead to dry eye syndrome and can also induce inflammatory factors, including TNF-α and IL-6." (PMID 32674521, 2020). "Several studies have shown direct association and increased expression levels of inflammatory cytokines IL-6, TNF-α, MCP-1, and MMP-9 in tears of dry eye patients." (PMID 30519584, 2018). "IL-1α, IL-6, IL-12, IFN-γ, and RANTES have been documented to be increased in the tears of dry eye patients." (PMID 28379171, 2017). "Increased levels of multiple cytokines including interleukin-6 (IL-6), interleukin-8 (IL-8), and tumor necrosis factor-alpha (TNF-α) have been detected in both the tear fluid of patients with dry eye symptoms and also in animal models of the disease." (PMID 20824100, 2010). "Furthermore, the mRNA expression of tumor necrosis factor-α (TNF-α), interleukin-6 (IL-6), and IL-1β in HCECs is inhibited by RGD-Alg@MSCs, which indicated a strong anti-inflammatory effect, crucial for mitigating dry eye symptoms." (PMID 40991713, 2025). "Given that proinflammatory cytokines such as IL-1β, IL-6, IL-8, IL-10, interferon-γ (IFN-γ), and tumor necrosis factor-α (TNF-α) are elevated in dry eye patients under hyperosmotic conditions, curcumin emerges as a promising alternative therapeutic agent for DED." (PMID 41300436, 2025). "In an SS group, the concentrations of tear cytokines such as IL-17, TNF-a, and IL-6 were found to be significantly higher than in a non-SS dry eye group and control subjects." (PMID 40095328, 2025). "Earlier studies have shown that alterations of the tear cytokine profiles occur in DED patient, with elevated proinflammatory cytokine levels such as IL-1, IL-6, IL-8, and TNF-α shown to be strongly correlated with dry eye markers, leading to ocular surface damage and goblet cell reduction." (PMID 37771976, 2023). "Firstly, the extracellular ligand IL-6 directs T cell recruitment by regulating local chemokine secretion and chemokine receptor (CCR4, CCR5, CXCR3, etc.)expression on the CD3+ infiltrate, thus leading to the occurrence of dry eye." (PMID 36522768, 2022). "In addition, receiver operating characteristic curves were drawn to analyze the predictive value of IL-1, IL-6, and TNF-α in efficacy on xerophthalmia." (PMID 35130850, 2022). "In subjects without dry eye, only IL-6 significantly increased at 1 and 3 months postoperatively (p = 0.008, p = 0.016)." (PMID 34957146, 2021). "Finally, we believe that biological markers–IL-6 and VEGF–should be used to identify the biological effect of bevacizumab 0.05% eye drops in dry eye patients." (PMID 32502179, 2020). "Particularly, treatment with ALA in cultures of corneal epithelial cells and when it is topically applied to a dry eye animal model has anti-inflammatory activity, decreasing the release and expression of inflammatory factors (TNF-a, IL-6, IL-1β, and IL-8) regulated by the NF-κB pathway." (PMID 31137826, 2019). "Studies by Pflugfelder and others have shown that the concentrations of inflammatory cytokines such as IL-1a, IL-6, IL-8 and TNF-α are increased in the conjunctival epithelium of patients with Sjögren syndrome, which is characterized by severe dry eye symptoms." (PMID 30096194, 2018). "In the no dry eye group, 1 day postoperative concentration of IL-1β, IL-6, IL-8, MCP-1, TNF-α and IFN-γ were 51.42 ± 6.05, 119.51 ± 12.19, 443.92 ± 34.51, 2128.74 ± 215.64, 159.73 ± 12.98, and 51.54 ± 6.82 pg/ml, respectively." (PMID 27695117, 2016). "In the no dry eye group, the initial concentrations of IL-1β, IL-6, IL-8, MCP-1, TNF-α and IFN-γ were 2.11 ± 0.14, 13.36 ± 1.97, 143.83 ± 11.92, 55.49 ± 5.94, 9.04 ± 0.01 and 0.55 ± 0.19pg/ml, respectively." (PMID 27695117, 2016).
dry eye (continued). "Similarly, our study found that parameters of dry eye, such as TBUT and corneal staining scores, revealed significant correlations with the concentration of IL-6 in tears after cataract surgery." (PMID 27695117, 2016). "This is in agreement with previous studies in symptomatic, moderate dry eye patients, where there were no increases in levels of IL-1β, IL-6, IL-8/CXCL8, GRO-b, ICAM-1, TRAIL, or ephrin A5 in tear fluid." (PMID 20508732, 2010). "Activation of the cGAS-STING pathway induced the expression of CXCL10, IL-6 and IFN-β, which were reported to be increased in dry eye patients and dry eye mice, and CXCL10 could potentially serve as a biomarker of dry eye." (PMID 37735446, 2023). "Third, the correlation coefficients among PM2.5, IL-6 and VEGF concentrations were small but of importance because the mechanism of ocular surface damage caused by air pollution is similar to but not completely the same as that of dry eye." (PMID 36319699, 2022). "Previous studies have shown that mRNA expression levels of interleukin (IL)-1β, IL-6, IL-8, tumor necrosis factor (TNF)-α, interferon (IFN)-γ, and matrix metallopeptidase (MMP)-9 were significantly increased in tears and conjunctiva of dry eye patients compared to normal controls." (PMID 33921231, 2021). "A significant increasing trend of interleukin (IL)-6 was found in both dry eye and subjects without preexisting dry eye (p = 0.016, p = 0.008), while IL-8 and tumor necrosis factor alpha (TNF-α) were only found to be increased in subjects with dry eye postoperatively (p = 0.031, p = 0.031)." (PMID 34957146, 2021). "Inflammatory cytokines, like type I and type II interferons and IL-6, IL-1, and TNF-α as well as immunomodulatory cytokines like IL-10 and transforming growth factor β (TGF-β), have been identified as important players in SLE and are present in the tear of dry eye patients." (PMID 25893112, 2015). "Tear IL-6 has been found to be elevated in Sjogren’s and non-Sjogren syndrome dry eye patients." (PMID 26605353, 2014). "However, application of anti-IL-6 antibody eye drops to the dry eye model rat failed to prevent corneal epithelial injury (data not shown)." (PMID 21976951, 2011). "In another study in which IL-1β, IL-6, and pro-matrix metalloproteinase (MMP)-9 tear levels were measured in patients with different types of ocular diseases, including a group of 20 hyposecretive moderate dry eye patients, only proMMP9 was significantly increased in DED patients." (PMID 20508732, 2010). "In summary, we found that high expression levels of inflammatory factors (IL-6, and TNF-α) in tears of patients with concomitant exotropia were significant higher than the control, which could be a potential factor who promoted the occurrence of dry eye in the patients with concomitant exotropia." (PMID 34659636, 2021). "Researchers have also shown a significant increase in the expression of IL-6 and TNF-α in the tear fluid of the dry eye patients with MGD when compared with dry eye patients without MGD." (PMID 35685417, 2022). "Five inflammatory cytokines IL-1β, TNF-α, IL-6, IL-8, and IFN-γ, were examined and compared between subjects with and without dry eye." (PMID 34957146, 2021). "The baseline levels of IL-6, IL-8, and IFN-γ were significantly higher in subjects with dry eye than in subjects without dry eye (p < 0.001, p = 0.003, p = 0.019)." (PMID 34957146, 2021). "In previous studies, significantly increased levels of IL-1α, IL-6, and TNF-α RNA transcripts were found in the conjunctival epithelium in SS and non-SS dry eye patients compared with controls." (PMID 21976951, 2011). "However, the levels of IL-6 and IFN-γ were not significantly correlated with any of the dry eye-related markers." (PMID 34957146, 2021).
myocardial ischemia (99 papers, 2011 to 2026). A disorder of cardiac function caused by insufficient blood flow to the muscle tissue of the heart. "Collectively, these findings underscore the central role of interleukin-6 in the pathophysiological mechanisms underlying myocardial ischemia-reperfusion injury and highlight its potential as a key therapeutic target." (PMID 41347019, 2025). "The protective effect of the PPAR-γ agonist on TNF–α and IL-6 was described in earlier studies about forebrain ischemia/reperfusion injury and injury caused by myocardial ischemia/reperfusion." (PMID 35204074, 2022). "Myocardial ischemia is a potent stimulus that causes the activation of MCs in the heart and the release of cytotoxic mediators such as IL-6, TNF-α, and IL-1β." (PMID 34512339, 2021). "Among the top-regulated and down-regulated genes, some genes described in previous studies were associated with myocardial ischemia and they were significant up-regulated, including Cxcl2 and Il6." (PMID 26540270, 2015). "Further studies showed that the stimulus of cardiac ischemia/reperfusion caused a remarkable increase in the expression levels of interleukin-1β (IL-1β), IL-6, and tumor necrosis factor-α (TNF-α) mRNA in ischemic heart tissue, which was effectively prevented by pretreatment with SIN." (PMID 35837272, 2022). "Other studies have reported that cardiac ischemia in mice hearts causes increased IL-6." (PMID 34070090, 2021). "In the early stage of myocardial ischemia reperfusion, inflammatory factors such as IL-6 and hs-CRP activate white blood cells, causing them to adhere to the microvascular endothelial cells in the ischemic area, resulting in endothelial cell atrophy, rupture, and finally necrosis." (PMID 33995051, 2021). "Despite the well-established pro-inflammatory nature of IL-6 in myocardial ischemia, a recent meta-analysis reports a limited contribution of IL-6 in the cardiac remodeling of hearts in animal models of myocardial ischemia." (PMID 41543641, 2026). "Strong stimulation, such as myocardial ischemia, activates myocardial cells and releases cytotoxic mediators such as IL-6, TNF-α, and IL-1β." (PMID 40298805, 2025). "A recent meta-analysis revealed a limited role of IL-6 in cardiac remodeling in animal models with myocardial ischemia, despite the well-established pro-inflammatory role of IL-6 in MI." (PMID 40428204, 2025). "IL-34 regulates the expression of proinflammatory cytokines (IL-17A, IL-1 and IL-6), which are classical cytokines involved in myocardial ischemia‒reperfusion (MI/R) injury." (PMID 39883639, 2025). "In myocardial ischemia/reperfusion models, Rg2 treatment significantly inhibited the expression of TNFα, IL-1β, IL-6, and monocyte chemoattractant protein-1 (MCP-1)." (PMID 41155644, 2025). "The compound effectively inhibited TNF-α, IL-1β, and IL-6 levels in myocardial ischemia–reperfusion models while suppressing necroptosis through transforming growth factor-beta-activated kinase 1 (TAK1) phosphorylation regulation." (PMID 41155644, 2025). "As well as cinnamic acid decreased serum levels of CK-MB, LDH, TNF-α, and IL-6, and myocardial ischemia increased serum NO activity." (PMID 37368609, 2023). "As IL-6 inhibition had markedly reduced biomarkers of thrombosis, IL-6 is thought to be a major contributing factor in myocardial ischemia and atherothrombotic complications." (PMID 37996879, 2023). "CuNP addition reduced the inflammatory milieu in the heart of mice with myocardial ischemia, thereby blocking the upregulation of proinflammatory cytokines (interleukin-1β (IL-1β), tumor necrosis component alpha (TNFα), and interleukin 6 (IL-6)." (PMID 37893319, 2023). "Combined with the results of our analysis, it is reasonable to suspect that IL-6 plays a role in myocardial ischemia–reperfusion by influencing ferroptosis." (PMID 36091399, 2022).